RPLP0 (ribosomal protein lateral stalk subunit P0)
Description:
Ribosomal protein P0 is the functional equivalent of E.coli protein L10.
Synonyms: PRLP0; P0; L10E; RPP0; LP0; uL10
Tractability: Small molecule: an approved drug acts on it; a structure with a bound ligand is known; a high-quality ligand is known. PROTAC: UniProt records ubiquitination sites on it; ubiquitination databases record sites on it; its protein half-life has been measured; a small molecule that binds it is known. Other modalities: a drug acting on it is in phase 2 or 3 trials.
Gene: Protein-coding gene on chromosome 12 (120,196,699 to 120,201,235, reverse strand). Ensembl gene ENSG00000089157.
Subcellular location: Nucleus; Cytoplasm
Subcellular location (Human Protein Atlas): Cytosol; Endoplasmic reticulum
Pathways (Reactome):
Metabolism of proteins: Eukaryotic Translation Termination; Formation of a pool of free 40S subunits; GTP hydrolysis and joining of the 60S ribosomal subunit; L13a-mediated translational silencing of Ceruloplasmin expression; PELO:HBS1L and ABCE1 dissociate a ribosome on a non-stop mRNA; Peptide chain elongation; Ribosome Quality Control (RQC) complex extracts and degrades nascent peptide; SRP-dependent cotranslational protein targeting to membrane; ZNF598 and the Ribosome-associated Quality Trigger (RQT) complex dissociate a ribosome stalled on a no-go mRNA
Metabolism of RNA: Major pathway of rRNA processing in the nucleolus and cytosol; Nonsense Mediated Decay (NMD) enhanced by the Exon Junction Complex (EJC); Nonsense Mediated Decay (NMD) independent of the Exon Junction Complex (EJC)
Cellular responses to stimuli: Response of EIF2AK4 (GCN2) to amino acid deficiency
Developmental Biology: Regulation of expression of SLITs and ROBOs
Disease: Viral mRNA Translation
Immune System: Gene and protein expression by JAK-STAT signaling after Interleukin-12 stimulation
Metabolism: Selenocysteine synthesis
Gene Ontology:
Molecular function: protein binding; RNA binding; structural constituent of ribosome; large ribosomal subunit rRNA binding
Biological process: cytoplasmic translation; negative regulation of myoblast fusion; spermatogenesis; striated muscle contraction; translation; ribosome biogenesis
Cellular component: cytoplasm; cytoplasmic ribonucleoprotein granule; cytosol; cytosolic large ribosomal subunit; cytosolic ribosome; extracellular exosome; focal adhesion; membrane; nucleus; postsynapse; postsynaptic density; ribonucleoprotein complex
Genetic constraint (gnomAD): Loss-of-function variants: 0 observed, 30.33 expected, observed/expected ratio (o/e) 0, 90% interval 0 to 0.098. The upper end of that interval is the gene's LOEUF score, 0.098, which puts it in group 1 of 6, group 1 being the genes least tolerant of losing a copy. Missense variants: 276 observed, 411.26 expected, observed/expected ratio (o/e) 0.67, 90% interval 0.61 to 0.74. Synonymous variants: 137 observed, 155.48 expected, observed/expected ratio (o/e) 0.88, 90% interval 0.77 to 1.01.
Homologues: Orthologues: chimpanzee RPLP0 (100% identical), tropical clawed frog rplp0 (91% identical), zebrafish rplp0 (88% identical), Drosophila melanogaster RpLP0 (68% identical), Caenorhabditis elegans rla-0 (67% identical). Paralogues in human: RPLP1 (17% identical), RPLP2 (17% identical).
Diseases named in the same sentence as RPLP0 in open-access papers:
RPLP0 is named in the same sentence as 81 diseases in open-access papers, as found by Europe PMC text mining. Sharing a sentence is not in itself a finding about the gene and the disease. The quoted sentences say what the papers report.
breast carcinoma (11 papers, 2007 to 2026). "Moreover, it has been demonstrated that patients with high expressions of RPLP0 are prominently associated with poor prognosis in clear cell renal cell carcinoma and breast cancer." (PMID 35342398, 2022). "Different studies have shown the over-expression of RPLP0 in tumor tissue, especially gynecological tumors, breast cancer, and gastric cancer." (PMID 34445327, 2021). "The TFRC and RPLP0 identified by us have been previously reported as reference genes in other cell types, including dexamethasone-exposed breast cancer cells and CD19-positive chronic lymphocytic leukemia cells." (PMID 25193495, 2014). "Some reference genes included in the study (e.g. RPLP0) have been shown to be unregulated by estrogen in human breast cancer cells." (PMID 23363446, 2013). "In pathway enrichment analysis for up regulated genes, genes such as RPLP0 and MRPS30 were associated with pathogenesis of many cancer types such as gastric cancer and breast cancer, but these genes may be responsible for advancement of GBM." (PMID 31137733, 2019). "Except for the endometrial carcinoma, ovarian cancer, and colon carcinoma, RPLP0, as a vital member of the RPLP family, is also upregulated in acute myeloid leukemia, clear cell renal cell carcinoma, and breast cancer." (PMID 35342398, 2022). "When examining the 18 patient tissue specimens (ER+/ER- IBC/normal) or the breast cancer tissue specimens alone (ER+/ER- IBC), the 3-gene combination of RPLP0, TBP and PUM1 were consistently identified by geNorm to exhibit the highest degree of stability." (PMID 18211679, 2008). "On the basis of our findings, we suggest that TFRC is the most stable EC, ACTB and TFRC is the best combination of two reference genes to quantify uPA, and that using RPLP0 and GAPDH are not recommendable for breast cancer." (PMID 21702980, 2011).
depression (4 papers, 2011 to 2025). "Then, we measured the concentrations of ALOX15B (also known as Alox8 in mice), RPLP0 and HP in our depression mouse model." (PMID 37942417, 2023). "Furthermore, ferroptosis-related genes, such as ALOX15B (Arachidonate-15-Lipoxygenase, Type B) and RPLP0 (ribosomal protein lateral stalk subunit P0), have been identified as potential biomarkers for diagnosing depression." (PMID 40177374, 2025). "The other YWHAZ abnormalities were the interactions with RNPS1 and LGALS1 in schizophrenia; the interactions with MYCBP2, PRDX1 or TP1l in bipolar disorder; the interactions with RPLP2 and VIM in major depression; and the interactions with RPLP0 in both schizophrenia and major depression." (PMID 22373040, 2011). "After analysis and comparison using three different statistical methods, B2M and RPLP0 were identified as the most suitable HKGs for gene expression studies in uncultured CD4+ T cells of asthmatics with or without depression." (PMID 23110234, 2012).
gastric cancer (4 papers, 2018 to 2022). A primary or metastatic malignant neoplasm involving the stomach. "RPLP0 contributes to the onset and development of gastric cancer and gynecologic tumors." (PMID 35342398, 2022). "The down-regulation of RPLP0 led to G1 arrest of gastric cancer cells." (PMID 35342398, 2022). "RPLP0 also affects the expression of p21 and has anti-apoptotic effect on gastric cancer." (PMID 29532746, 2018).
melanoma (4 papers, 2016 to 2022). A malignant, usually aggressive tumor composed of atypical, neoplastic melanocytes. "In addition, we identify five genes (ALG12, GUSB, RPLP0, KRBA2, and ADAT2) that are stably expressed in melanoma cells independent of the presence of T cells or the T cell-derived cytokines IFNγ and TNFα." (PMID 27625650, 2016).
Obesity (4 papers, 2020 to 2026). Accumulation of substantial excess body fat. "Furthermore, to assess the overall stability of each gene during the development of obesity, the data at the four time points were included in the analysis, and the result showed that PPIA, RPLP0, and YWHAZ were more stable in expression." (PMID 33330591, 2020). "During the past decades, β-actin (ACTB), glyceraldehyde-3-phosphate dehydrogenase (GAPDH), 18S ribosomal RNA (18S), ribosomal protein large P0 (RPLP0), and TATA box-binding protein (TBP) have been used extensively as reference genes in physiological status and diseases including obesity." (PMID 33330591, 2020). "Nonetheless, whether the corresponding proteins translated from more stably expressed genes PPIA, RPLP0, and YWHAZ are appropriate for references in protein studies of obesity, needs to be clarified in the future." (PMID 33330591, 2020).
colon carcinoma (3 papers, 2010 to 2025). "Specifically, these approaches used distinct reference genes (PCBP1 for DNA-based detection in colon cancer and RPLP0 for RNA-based detection in rectal cancer), which may affect direct comparability between cohorts." (PMID 41019049, 2025).
ovarian carcinoma (3 papers, 2014 to 2022). A malignant neoplasm originating from the surface ovarian epithelium. "From the 12 candidate reference genes we studied, the combination use of ACTB, PPIA, RPLP0, and TBP was identified as a relatively superior normalization strategy, while GAPDH was insufficient for accurate normalization when considering its overexpression in ovarian cancer." (PMID 24776823, 2014). "Given that HRPT1 and B2M were expressed differently in the 50 specimens, which suggested that these two genes were not eligible reference genes, the combination of ACTB, RPLP0, PPIA, and TBP was recommended for use in epithelial ovarian cancer studies." (PMID 24776823, 2014).
schizophrenia (3 papers, 2011 to 2019). A major psychotic disorder characterized by abnormalities in the perception or expression of reality. "Genes with the least variable localization included components of the ubiquinol-cytochrome c reductase complex (Uqcrq, Uqcr11), ATP synthase complex (Atp5e, Atp5k), and ribosomal subunits (Rplp0, Rps25), some of which in humans have been implicated in schizophrenia and schizoaffective disorder." (PMID 30678683, 2019). "While Silberberg and colleagues found TFRC and RPLP0 as the most stable reference genes in schizophrenia and bipolar disorders, Penna and colleagues found CYC1 and EIF4A2 as the best reference genes in Alzheimer’s disease." (PMID 27754318, 2016).
bladder cancer (2 papers, 2020 to 2025). "We demonstrated its abnormal overexpression in tumor tissues and further showed that intratumoral RPLP0 knockdown in a subcutaneous bladder cancer model could enhance the efficacy of immunotherapy." (PMID 40777041, 2025). "As they consistently ranked in the top ten by CoV, GeNorm and Normfinder, UBC, RPLP0, HMBS, GUSB, and TBP are the most suitable endogenous control genes for bladder cancer qPCR." (PMID 33057113, 2020).
breast tumor (2 papers, 2011 to 2024). "The expression of six HKs (TFRC, GUSB, GAPDH, ACTB, HPRT1 and RPLP0) was investigated using geNorm and NormFinder softwares in forty breast tumor, four normal and eight adjacent tissues." (PMID 21702980, 2011).
cervical cancer (2 papers, 2021). A primary or metastatic malignant neoplasm involving the cervix. "A recent study highlights that down-regulation of RPLP0 decreases cell viability and cell proliferation and increases cell death in HtTA cervical cancer cells." (PMID 34445327, 2021). "In cervical cancer, RPLP0 KD decreases cell viability and proliferation while increasing apoptosis level." (PMID 34873618, 2021). "In cells overexpressing the tumor suppressor gene phospholipase A and acyltransferase 4 (PLAAT4), RPLPO levels are decreased suggesting that the ratio of RPLP0 to PLAAT4 is an important regulator of cervical cancer growth and development." (PMID 34873618, 2021).
colitis (2 papers, 2017 to 2023). Inflammation of the colon. "In contrast, our comparative study of candidate reference genes suggested the use of TBP/Rplp0 as the appropriate reference genes for target gene normalization in C57BL/6 mice associated with DNBS- experimental colitis model." (PMID 28186172, 2017).
colorectal cancer (2 papers, 2016 to 2021). A primary or metastatic malignant neoplasm that affects the colon or rectum. "As the results of transcriptional analysis depend on genes used as normalizers, we used several internal controls, namely the most popular (GAPDH), the pair of genes previously found to be stably expressed in colorectal cancer (PPIA and RPLP0), and RN18S1, which all yielded consistent results." (PMID 34884259, 2021).
endometrial carcinoma (2 papers, 2022 to 2024). A malignant tumor arising from the epithelium that lines the cavity of the uterine body. "Furthermore, compared with normal tissues, RPLP0, RPLP1and RPLP2 are significantly up-regulated in gynecologic tumors such as ovarian and endometrial cancers, suggesting that these proteins can be used as specific prognostic markers and related therapeutic targets for gynecological tumors." (PMID 39684863, 2024).
Hyperglycemia (2 papers, 2014 to 2025). An increased concentration of glucose in the blood. "Under hyperglycemia combined with hypoxia up to 12 hr, the expression of RPLP0, TFRC, GUSB, and ACTB genes remained unchanged." (PMID 25193495, 2014). "Under hypoxia as well as under hyperglycemia and hyperglycemia combined with hypoxia for different time intervals (1, 3, and 12 hr), RPLP0 was predicted to be the most stable expressed reference gene." (PMID 25193495, 2014). "Under hyperglycemia combined with hypoxia, gene expression of GUSB, TFRC, RPLP0, and ACTB turned out to be stable in all time intervals measured (1, 3, and 12 hr)." (PMID 25193495, 2014). "Our findings strongly confirm that RPLP0 and TFRC are the most suitable reference genes for HUVEC gene expression experiments subjected to hypoxia and/or hyperglycemia for the given experimental conditions." (PMID 25193495, 2014). "Therefore, this is the first report indicating TFRC and RPLP0 as suitable reference genes in HUVEC exposed to hypoxia, hyperglycemia, or hypoxia and hyperglycemia combined." (PMID 25193495, 2014). "In contrast, we applied shorter incubation times (1, 3, and 12 hr) and identified two reference genes, namely RPLP0 and TFRC, as the most stably expressed under both euglycemia and hyperglycemia, in the presence or absence of hypoxia." (PMID 25193495, 2014).
lung carcinoma (2 papers, 2022 to 2024). "The results exhibited that the level of RPLP0 was signally overexpressed in the five NSCLC cell lines relative to that in normal lung cancer cells, among which the level of RPLP0 was higher in A549 and NCI-H1299 cells relative to that in the other three cell lines." (PMID 35342398, 2022). "Thus, the level of miR-4731-5p and RPLP0 was related in the prognosis of lung cancer patients." (PMID 35342398, 2022). "Although the previous study reports that RPLP0 always acts as a reference gene for gene expression studies on NSCLC, more and more literature confirm that RPLP0 is differently expressed in lung cancer." (PMID 35342398, 2022).
rectal cancer (2 papers, 2022 to 2025). A primary or metastatic malignant neoplasm that affects the rectum. "Meanwhile, although the mRNA level of RPLP0 was upregulated in the most of rectal cancer tissues, the protein level of RPLP0 only increased in 13/24 tissues." (PMID 35974014, 2022). "In this study, we observed the upregulation of RPLP0 in locally advanced rectal cancer tissues and its higher expression was correlated with radioresistance of rectal cancer patients." (PMID 35974014, 2022). "We further evaluated the clinical significance of NONO and RPLP0 in patients with locally advanced rectal cancer (LARC)." (PMID 35974014, 2022). "Interestingly, the Duolink PLA assay in specimens obtained from patients with rectal cancer showed that the binding between NONO and RPLP0 was mainly observed in the nuclei of tumor cells, but not in those of adjacent non-tumor cells." (PMID 35974014, 2022).
T-cell lymphoma (2 papers, 2017 to 2021). "To identify suitable reference genes during T-cell lymphoma development, we investigated the expression stabilities of eight commonly used candidate reference genes (Gapdh, Rn18s, Actb, Hprt, B2M, Rplp0, Gusb, and Ctbp1) by RT-qPCR at different time points following the administration of MNU." (PMID 28807016, 2017). "In conclusion, we identified Ctbp1 and Rplp0 as the best reference genes for thymus and spleen, respectively, in an MNU-induced T-cell lymphoma mouse model." (PMID 28807016, 2017).
viral infections (2 papers, 2013 to 2021). "The cellular RPLP0 was observed as up-regulated after virus infection, such as pseudorabies virus (PrV) infected bovine kidney cells, and Epstein-Barr virus (EBV) infected primary B cells." (PMID 23855489, 2013).
acute leukemia (1 paper, 2024). A clonal (malignant) hematopoietic disorder with an acute onset, affecting the bone marrow and the peripheral blood. "Therefore, our study proposes the set of endogenous genes ACTB, ABL, TBP and RPLP0 as the most appropriate for the analysis of expression assays of acute leukemia samples." (PMID 38397141, 2024). "In order to identify the best reference genes for gene expression studies in peripheral blood and/or bone marrow samples of acute leukemia patients, a qPCR assay based on TaqMan detection for the expression analysis of the six selected genes (ACTB, ABL, GAPDH, HPRT, TBP and RPLP0) was used." (PMID 38397141, 2024).
acute monocytic leukemia (1 paper, 2024). Acute monoblastic leukemia (AML-M5), is one of the most common subtypes of acute myeloid leukemia (AML) that is either comprised of more than 80% of monoblasts (AML-M5a) or 30-80% monoblasts with (pro)monocytic differentiation (AML-M5b). "FXR1 is elevated in G0 and chemosurviving acute monocytic leukemia (AML) cells, and this resistance-phenotype seems to be driven by a variety of ribosomal alterations, one of them being an increase in the incorporation of the ribosome stalk protein uL10 (RPLP0)." (PMID 38989007, 2024).
autism (1 paper, 2023). Persistent deficits in social interaction and communication and interaction as well as a markedly restricted repertoire of activity and interest as well as repetitive patterns of behavior. "Although the association of these genes with autism is not entirely determined yet, they could be a potential signature for autism since all of them except for RPLP0 are reported to be involved in neurological issues." (PMID 36691005, 2023).
autoimmune disease (1 paper, 2023). A disorder resulting from loss of function or tissue destruction of an organ or multiple organs, arising from humoral or cellular immune responses of the individual to their own tissue constituents. "The ribosomal stalk, consisting of acidic ribosomal proteins RPLP0, RPLP1, and RPLP2, played an essential role in promoting translation subsets of cellular mRNAs, and closely linked to several pathological conditions, including autoimmune diseases and human malignancies." (PMID 37980521, 2023).
axonal neuropathy (1 paper, 2006). Any nerve disorder affecting the axon of a nerve. "In CMT2L, an axonal neuropathy, the assigned locus contains 26 candidate genes, including the RPLP0 gene." (PMID 17183665, 2006).
cervical tumor (1 paper, 2022). "RPLP0 has been found to regulate cell apoptosis and cycle arrest of cervical tumor cells." (PMID 35342398, 2022).
colon adenocarcinoma (1 paper, 2016). "Normalization against PPIA/RPLP0/SDHA was found optimal for studies involving various colon adenocarcinoma cell lines subjected to manipulations of serum availability." (PMID 27339468, 2016).
ductal carcinomas (1 paper, 2022). "To investigate if LaNt α31 expression is linked to proliferation, we used inhibited cell division using mitomycin c in two widely used cell lines derived from malignant ductal carcinomas, MCF7 and MDA-MB-231, then quantified LAMA3LN1 transcript abundance using RT-qPCR normalised to GAPDH and RPLP0." (PMID 35231053, 2022).
embryonal carcinoma (1 paper, 2022). A non-seminomatous malignant germ cell tumor characterized by the presence of large germ cells with abundant cytoplasm resembling epithelial cells, geographic necrosis, high mitotic activity, and pseudoglandular and pseudopapillary structures formation. "Mutations in ADAMTS20, ARHGAP10, OR1L4, PDS5A, and RPLP0 were only found in mixed germ cell tumors, while mutations in B3GNT8, CAPN7, FAT4, GRK1, TACC2 and TRAM1L1 were only observed in embryonal carcinoma, and their mutation frequency was around 2%." (PMID 36713456, 2022).